KIF11 (kinesin family member 11)
Diseases named in the same sentence as KIF11 in open-access papers (continued):
Sharing a sentence is not in itself a finding about the gene and the disease.
tumor (121 papers, 2009 to 2026). "In our analysis, we observed a trend toward increased KIF11 expression with higher tumor grading, suggesting a potential association between KIF11 and more aggressive tumor phenotypes." (PMID 40075652, 2025). "Further studies are needed to elucidate the molecular mechanisms underlying KIF11-mediated tumor progression and to determine its potential as a therapeutic target." (PMID 40075652, 2025). "For example, aberrant KIF11 expression has been associated with the facilitation of tumor proliferation, invasion, and migration." (PMID 38433242, 2024). "Consisting with its role in cell division, numerous studies showed that KIF11 was implicated in human tumor." (PMID 36742345, 2022). "Correlation analysis further confirmed that high KIF11 expressions were positively associated with tumor grades (p < 0.001), lymphatic metastasis (p < 0.001), and clinicopathological stages (p < 0.001)." (PMID 35619540, 2022). "The immune score, stromal score, and ESTIMATE score were negatively associated with tumor stage, and there was statistical significance in the association between scores and KIF11 expression." (PMID 33968780, 2021). "Our experiments implicated knockdown of KIF11 by lentiviral-mediated shRNA inhibits tumor cell growth in vitro and in vivo." (PMID 33490265, 2021). "High KIF11 expression contributes to tumor progression and is associated with unfavorable prognosis." (PMID 32219041, 2020). "Inhibition of the Id target Kif11 (with ispinesib treatment) in combination with chemotherapy also resulted in a loss of Id+ CSC subpopulations of tumor cells, ultimately leading to more effective debulking of the entire tumor." (PMID 32911668, 2020). "KIF11 encodes for a mitotic spindle protein and was previously identified to be tumor-lethal in HNSCC11." (PMID 32047167, 2020). "In vivo, interfering with KIF11/Eg5 function causes developmental and vascular defects in zebrafish and chick embryos and potent inhibition of tumor angiogenesis in experimental tumor models." (PMID 24327603, 2013). "The point mutation of loop 5 in tumor cells contributes to the resistance of KIF11 inhibitors." (PMID 38672404, 2024). "Overexpression of KIF11 is associated with tumor grade and poor OS." (PMID 38672404, 2024). "Overexpression of KIF11 is associated with tumor nuclear grade, TNM stages, and poor OS." (PMID 38672404, 2024). "Moreover, our clinical data as well as the TCGA database showed KIF11 expression was abundant in most CCA tumor specimens and associated with poor outcomes of CCA patients." (PMID 36123339, 2022). "However, the low staining extent of tumor cells for KIF11 was marginally significantly associated with the occurrence of perineural invasion (p = 0.05, Fisher’s exact test)." (PMID 34208606, 2021). "Association of KIF11 inhibitor 4bt in drug combination treatment regimen besides to cause a decrease in tumor volume it also caused a considerable reduction in intratumoral necrotic area, even better than AC-T drug combination, showing important antiproliferative activity in this tumor model." (PMID 34548908, 2021). "KIF11 depletion inhibits cell proliferation and tumor growth in vitro and in vivo, making it a potential prognostic marker and therapeutic target for HCC." (PMID 40546347, 2025). "In SCLC, RNA expression of KIF11 was correlated with the proliferation marker Ki-67, an established prognostic indicator of tumour aggression." (PMID 40002279, 2025). "Using immunohistochemical analysis of 92 tumor samples, we demonstrated that high KIF11 and low KIF14 expression correlate with poor patient outcomes, suggesting their combined evaluation offers superior prognostic value." (PMID 40075652, 2025). "Tumor tissues resected from filanesib-treated mice were immunostained with KIF11, a target protein of the compound." (PMID 40281281, 2025). "Immunohistochemical analysis of 92 tumor samples showed that high KIF11 and low KIF14 expression are independent indicators of poor overall survival." (PMID 40075652, 2025).
tumor (continued). "All untreated tumor tissues showed relatively high expression of KIF11, and the staining was mainly localized in the cytoplasm." (PMID 40281281, 2025). "In HB-279 and HB-284 tumors, the number of KIF11-positive cells was lower in filanesib-treated tumor tissues than in controls." (PMID 40281281, 2025). "When KIF11 is absent, KIF15 (another member of the kinesin superfamily) can construct a complete bipolar spindle, leading to the proliferation of tumor cells that escape repression from the KIF11 inhibitors." (PMID 38672404, 2024). "Immunohistochemical staining and Western blotting were used to observe the expression of risk model factors PRR11, KIF11, RACGAP1 as well as the potential common transcription factors YY1, CREB1 and SUZ12 in HCC tissues and para-tumor tissues." (PMID 39530087, 2024). "KIF11 is involved in the cell cycle, tumor microenvironment alternation, and tumor-infiltrating immune cell proportions; upregulated KIF11 results in higher infiltration levels." (PMID 38672404, 2024). "Regarding GBC, KIF11 transfection was determined to be capable of facilitating tumor growth via an effect on the ERBB2/PI3K/Akt signaling pathway." (PMID 38433242, 2024). "It has been reported that KIF11 is involved in the G2/M phase transition and promotes tumor progression by regulating cell cycle checkpoints." (PMID 39624268, 2024). "KIF11 is a novel kinesin superfamily that influences childhood lymphoblastic leukemia and mediates cell cycle and migratory capacity in tumor cells." (PMID 39624268, 2024). "Upregulated KIF11 is related to poor OS and positively related to immune infiltration, tumor size, T stage, pathological stages, and tumor recurrence rate within 2 years." (PMID 38672404, 2024). "Other results have demonstrated that inhibiting KIF15 hinders tumor cells from developing resistance to KIF11 inhibitors." (PMID 38672404, 2024). "Combined, these data indicate that synergistic targeting of KIF11 and AURKA with specific inhibitors causes a significant delay in tumor growth and improved overall survival compared to single drugs alone." (PMID 37894278, 2023). "Involved in the G2/M phase transition, KIF11 contributes to influence tumor progression by regulating cell cycle checkpoints." (PMID 37656243, 2023). "The role of NEAT1 and KIF11 in cellular senescence and tumor growth in HCC was assessed both in vitro and in vivo." (PMID 37752791, 2023). "The approach of using a KIF11 inhibitor to enrich tumor cells in mitosis prior to radiotherapy has strong rationale." (PMID 37370783, 2023). "Ispinesib (SB-715992) is a highly specific KIF11 inhibitor, which widely exerts the anti-tumor activity through maintaining the complete response." (PMID 37656243, 2023). "In our current study, we performed expression analysis of kinesin family in LUAD which revealed overexpression of KIF11/12/15/23/18B/20A/2C/4A/C1 in tumor samples whereas KIF17/26A/1C were underexpressed in LUAD." (PMID 37330525, 2023). "In vitro evidences have validated the role of KIF11 in mediating migratory capacity and angiogenesis of tumor cells." (PMID 37656243, 2023). "The same trend of TACC3 or KIF11 expression level was verified by the Western blotting of collected subcutaneous tumor tissue." (PMID 38012214, 2023). "Six of them (KIF4A, ASPM, KIF20A, KIF14, TPX2, KIF18B) are overexpressed by more than 10-fold in tumor samples and four of them (KIF11, AURKB, TPX2 and KIFC1) are essential for cell survival." (PMID 37835564, 2023). "Knockdown of TACC3 and its downstream protein KIF11 inhibits tumor cell proliferation and increases chemosensitivity in PDAC." (PMID 38012214, 2023). "We next investigated publicly available databases to assess the RNA expression of transcripts encoding for KIF11, KIF15, TPX2, and AURKA in EWS patient tumor samples using BioGPS (E-GEOD-12102)." (PMID 37894278, 2023). "Pharmacological inhibition of TACC3 or KIF11 can suppress tumor cell proliferation and promote apoptosis." (PMID 38012214, 2023).
tumor (continued). "The expression of KIF11 was diverse in different molecular and immune subtypes and remarkably correlated with immune cell infiltration in the tumor microenvironment." (PMID 36742345, 2022). "The immunohistochemistry (IHC) staining showed that KIF11 expression levels were not only high in tumors versus normal samples but correlated with high tumor grades." (PMID 35619540, 2022). "Similar to TOP2A, KIF11, acting as an oncogene that promotes the proliferation of tumor cells, is negatively correlated with decreased overall survival." (PMID 36589233, 2022). "Taken together, our study validated that KIF11 was higher in tumor samples versus normal tissues, in line with the previous results." (PMID 35619540, 2022). "Immunohistochemistry (IHC) staining showed that KIF11 expression was higher in CCA tumors compared to para-tumor (liver) and normal (intrahepatic bile duct) tissues." (PMID 36123339, 2022). "The immunohistochemical staining results furtherly confirmed that lymph node showed higher KIF11 expression level in both normal and tumor tissues." (PMID 36742345, 2022). "CCA showed a higher KIF11 gene dependency across various tumor types, suggesting the potential therapeutic intervention of targeting KSP." (PMID 36123339, 2022). "We utilized bioinformatics analysis to identify that KIF11 expressed highly in tumor samples versus paired normal tissues and high KIF11 correlated with high clinical stages of patients." (PMID 35619540, 2022). "Differential analysis suggested that KIF11 expressed highly in tumor cases compared with those in normal tissues, and the results were consistently confirmed in multiple PDAC data sets and resected fresh PDAC samples." (PMID 35619540, 2022). "KIF11, known as mitotic spindle-specific protein, and its oral inhibitor 4SC-205 demonstrates anti-tumor activity and enhances targeted therapy in primary and metastatic neuroblastoma models." (PMID 36176446, 2022). "Second, we observed that KIF11 was correlated with immune cell infiltration in the tumor microenvironment." (PMID 36742345, 2022). "The differential analysis was conducted to find that KIF11 mRNA levels were notably upregulated in tumor samples relative to those in normal tissues with p < 0.001." (PMID 35619540, 2022). "KIF11 showed strong relationships with pathological stage, prognosis, tumor stemness, genomic heterogeneity, neoantigens, ESTIMATE, immune checkpoint, and drug sensitivity." (PMID 36742345, 2022). "Considering the role of KIF11 in tumor progression and immune cell infiltration, we verified the relationship between KIF11 expression and therapeutic response in different tumors." (PMID 36742345, 2022). "The potential relationship between genetic alteration of KIF11 and the prognosis of patients indicated that tumor patients with genetic alterations in KIF11 showed better OS, DSS, and PFS than patients without alterations." (PMID 36742345, 2022). "We further investigated the functional roles of KIF11 in PDAC and KIF11 overexpression significantly promoted tumor cell growth, migration, and self‐renewal potentialities." (PMID 35619540, 2022). "Several mitosis-associated genes, including AURKA, DLGAP5, TPX2, KIF11, and CKAP5, were overexpressed in tumor tissues, and associated with cell proliferation and poor OS." (PMID 36499051, 2022). "Silencing of KIF11 led to marked mitotic arrest with an observation of the mono-astral spindle phenotype and inhibition of tumor proliferation and growth." (PMID 33995648, 2021). "A stably KIF11-depleted cell line was established by screening for puromycin to study the mechanism by which KIF11 affected tumor progression." (PMID 33490265, 2021). "We found that KIF11 was upregulated in CRC tissues and was associated with advanced clinical stage and vessel invasion and that knockdown of KIF11 led to tumor growth arrest and increased sensitivity to oxaliplatin via enhanced DNA damage and apoptosis." (PMID 33995648, 2021).
tumor (continued). "Tumor core was enriched with actively dividing cells marked by KIF11+ mitotic figures, a good target for ispinesib." (PMID 34079014, 2021). "We have also shown that there is a correlation between KIF11 expression levels and inhibition of tumor progression." (PMID 34548908, 2021). "KIF11 likely promotes tumor cell mitosis and cell proliferation through ERBB2/PI3K/AKT signaling pathway." (PMID 33613109, 2021). "Knockdown of KIF11 markedly impaired tumor growth in vitro and in vivo and sensitized CRC cells to oxaliplatin via enhanced DNA damage and apoptosis." (PMID 33995648, 2021). "Normal brain parenchyma was devoid of KIF11 expression, interfacing with tumor core densely packed with tumor cells." (PMID 34079014, 2021). "Immunohistochemical analyses of the human GBC cells xenografted in nude mice showed a low Ki67 and PCNA expression in KIF11-knockdown tumor tissues which were identified with the previous results." (PMID 33613109, 2021). "In this study, we found KIF11 enriched among ATRT tumors, and ispinesib (a KIF11 inhibitor) was an efficacious agent for this tumor type." (PMID 34079014, 2021). "High KIF11 expression significantly predicted an unacceptable overall and progression-free survival and was correlated with advanced tumor stage and grade." (PMID 33968780, 2021). "The correlation analysis revealed significant positive correlations were observed between EP300 and KIF11 in various tumor types." (PMID 33613109, 2021). "Filanesib is another promising targeted inhibitor of KIF11 that induces mitotic arrest and subsequent tumor cell death." (PMID 33968780, 2021). "We collected the clinical case information from 70 patients with HCC and used IHC staining to detect KIF11 expression in the patient's tissues and found that KIF11 was positively correlated with tumor size (p = 0.016)." (PMID 33490265, 2021). "It has been reported that KIF11 plays essential roles in G2/M phase transition and cell cycle checkpoints during mitosis, subsequently modulating tumor progression." (PMID 33968780, 2021). "Analysis results showed that mRNA expression levels of KIF11 were significantly higher in tumor than in normal control." (PMID 32346924, 2020). "The kinesin family member 11(KIF11) is one of the kinesin family motor protein members and is associated with spindle formation and tumor genesis." (PMID 32219041, 2020). "We found that this interphase pool of KIF11 was responsible for driving tumor cell invasion and process formation." (PMID 32811879, 2020). "KIF11 is needed for survival of GBM tumor initiating cells (TICs)—the most invasive and chemoresistant cells in this tumor—and is essential for driving both GBM invasion and proliferation." (PMID 32300151, 2020). "Subsequent BrdU incorporation assay revealed a significant decrease in tumor cell proliferation in KIF11-depleted Ben-Men-1 and NCH93 cells for both siRNAs employed." (PMID 30991738, 2019). "KIF11 knockdown inhibited tumor growth both in vitro and in vivo, and its expression was responsible for shorter survival time." (PMID 30898978, 2019). "Docetaxel resistant TNBC xenograft models were established to evaluate the efficacy of KIF11 inhibition on tumor progression in vivo." (PMID 29190901, 2017). "Castillo and colleagues have demonstrated proof of principle of a role for KIF11 overexpression in driving tumorigenesis, by showing that transgenic mice overexpressing KIF11 are prone to the development of a variety of different tumor types." (PMID 23585914, 2013). "Similar trends for the cell-cycle-associated genes (ASPM, CENPE, TPX2, TRIP13, KIF11, KIF20A) were observed with their distribution in different-grade tumors, with higher expression levels observed as tumor grade increased." (PMID 23506684, 2013). "KIF11 mRNA expression is reported to be elevated in tumor samples compared with adjacent normal tissue in tumors derived from breast, colon, lung, ovary, rectum and uterus." (PMID 19545421, 2009).
tumor (continued). "Eight downregulated and two upregulated hub genes (CDK1 and KIF11) in the tumor were identified." (PMID 40457491, 2025). "Our findings may help understand the biological processes underlying tumor development and progression and suggest CDK1 and KIF11 as possible key molecules in the development of CRC." (PMID 40457491, 2025). "Our analysis supported three kinesin genes (KIF4A, KIF20A, and KIF11) that may play a key role in tumor initiation and progression by regulating cell proliferation and division." (PMID 41462522, 2025). "However, our data suggest that KIF11 expression is regulated by factors beyond traditional histopathological characteristics such as tumor grade or patient age." (PMID 40075652, 2025). "Immunohistochemical tissue analyses of 90 patients affected by clear cell renal cell carcinoma, followed for 7 years, revealed a high expression of KIF11 in the cytoplasmic fraction compared to the nuclear fraction, and this was positively correlated with tumor grade and mortality." (PMID 38939361, 2024). "Adversely, ectopic KIF11 expression exerted a promotive effect on the regulation of tumor growth." (PMID 38433242, 2024). "KIF11-targeted intervention or its specific inhibitor Monastrol treatment, could strikingly induce G2/M cell cycle arrest and suppress tumor growth both in vitro and in vivo." (PMID 38433242, 2024). "Additionally, KIF11 is regulated at the transcriptional, post-transcriptional, and post-translational levels in tumorigenesis and tumor progression." (PMID 38672404, 2024). "KIF11 was highly expressed in LUAD compared to normal tissues and its high expression is correlated with poor overall survival and worse progression-free survival, in addition to the positive association with tumor grade." (PMID 38939361, 2024). "Studies focusing on the roles of KIF11 in the tumor microenvironment (TME) are relatively limited." (PMID 38672404, 2024). "To begin to investigate if KIF11 inhibition was capable of radiosensitizing GBM cells, we utilized clonogenic assays to quantify reproductive cell survival after irradiation as this approach is associated with the clinical response of a tumor to radiotherapy." (PMID 37370783, 2023). "In both cases, CoREs changed from A to B subcompartments in tumours, and this repositioning was concomitant with increased H3K27me3 levels and loss of chromatin interactions with XRCC5 and KIF11 promoters." (PMID 36922594, 2023). "The goal of our study was to validate the therapeutic efficacy of enriching GBM tumor cells in the phase of the cell cycle where they are most vulnerable to radiotherapy, mitosis, using a small molecule inhibitor to the mitotic kinesin, KIF11." (PMID 37370783, 2023). "In our studies, we sought to evaluate if the enrichment of GBM cells in mitosis, using an inhibitor to the mitotic kinesin KIF11, could increase overall tumor cell death due to the increased sensitivity of mitotic cells to irradiation." (PMID 37370783, 2023). "KIF11 is a member of the kinesin family, and this gene has been over-expressed in tumor tissues." (PMID 38077941, 2023). "These screens identified KIF11 as an essential protein in maintaining tumor cell viability." (PMID 37894278, 2023). "We next examined KIF11 expression in 107 tumor specimens from a human CCA cohort." (PMID 36123339, 2022). "Targeting the SREBP2‐driven MVA pathway (atorvastatin) could significantly suppress KIF11‐induced in vivo tumor growth." (PMID 35619540, 2022). "Furthermore, the potential associations between KIF11 expression and molecular subtypes, immune subtypes, neoantigen, ESTIMATE, immune checkpoint, and immune cell infiltration in the tumor microenvironment were analyzed." (PMID 36742345, 2022). "Notably, some previously reported genes, such as PSMA5 and KIF11, can be treated as potential therapeutic targets for tumours." (PMID 35421138, 2022).